VEGFA (vascular endothelial growth factor A)
Diseases named in the same sentence as VEGFA in open-access papers (continued):
Sharing a sentence is not in itself a finding about the gene and the disease.
tumor (continued). "NK cells modulate the inflammatory property of neutrophils via IFN-γ-stimulated pathway to inhibit the expression of vascular endothelial growth factor-A (VEGF-A) which promoted angiogenesis and subsequent tumor growth in a rodent model." (PMID 37212866, 2023). "This promotes the expression of angiogenic factors VEGFA and PDGFB, leading to an increase in tumor vascular density, and targeting this pathway for cancer therapy is effective." (PMID 37259059, 2023). "Mechanistically, SIRT7 selectively activated the IRE1α-XBP1 axis to potentiate the pro-survival ERK signal pathway and the secretion of tumor-promoting cytokines like IL-8, TNF-α and VEGFA." (PMID 36918544, 2023). "Our computer-based analysis revealed that the messenger (m)RNA levels of VEGFA, CTNNB1, MMP7, and CD44 oncogenic signatures were upregulated in tumor samples compared to normal samples of patients with CRC tissues, with significant p values (<0.05)." (PMID 36672201, 2023). "Combined with our finding that DHA affects VEGFA expression by directly regulating the LOXL2, it was reasonable to presume a synergistic anti-tumor effect of DHA combined with VEGFR-TKIs." (PMID 37056396, 2023). "RNA-sequencing revealed that TGF-β1 and TCM alter gene expression in HL-60 cells, including the mRNA levels of the pro-tumor oncostatin M (OSM) and vascular endothelial growth factor A (VEGFA)." (PMID 37682817, 2023). "Taken together, our study has demonstrated that USP22 is a novel co-regulator of ZEB1 to enhance ZEB1-induced VEGFA transcription via USP22 deubiquitination activity, thereby promoting tumor growth/invasion/VM formation and angiogenesis in HCC." (PMID 36906615, 2023). "Neutrophils in tumour‐invaded TDLN highly expressed AP (CD74 and HLA‐DPA1/DQA1), pro‐angiogenesis (VEGFA) and immunosuppressive (TGFBI)‐related genes." (PMID 37491740, 2023). "VEGFA combined with VEGFR2 triggers signalling cascade pathways and ultimately induces endothelial cell proliferation, survival and migration to promote tumour progression." (PMID 36729917, 2023). "The expression levels of MMP9, VWF, VEGFA, SERPINE1, and TIMP1 in ccRCC tissues were higher than those in normal tissues, while the expression of EGF in tumor tissues was lower." (PMID 36959648, 2023). "Therefore, bLF may inhibit tumor angiogenesis through VEGFA inhibition." (PMID 36678795, 2023). "ITGA5 and VEGFA were coexpressed in clusters 1 and 3, while ANGPT1 and ANGPT2 were minimally expressed in all tumor cells." (PMID 36999964, 2023). "The gene and protein expressions of VEGFA, E-cadherin, TGFβ1, EGFR, and bFGF in tumor cells were assayed at the 3 different doses of the anti-PD-L1 antibody." (PMID 38152616, 2023). "MSI2 binds the internal ribosome entry site (IRES)-containing oncogene mRNAs including MYC, JUN and VEGFA as well as HCV IRES to increase their synthesis and promote self-renewal and tumor-initiation at the post-transcriptional level." (PMID 37117191, 2023). "Like tocilizumab, bevacizumab is also a humanized IgG1 MAb that has the ability to bind with vascular endothelial growth factor A (VEGF), resulting in the apoptosis of tumor cells." (PMID 36851211, 2023). "Vascular Endothelial Growth Factor A (VEGFA) is another key player, mainly responsible for promoting angiogenesis, a fundamental process that provides the tumor with the necessary blood supply." (PMID 37964873, 2023). "The secreted protein genes WNT5A, VEGFA, and SEMA3A, and the receptor genes AXL, TNFRSF10B and IGF1R were mainly expressed by tumor cells." (PMID 37823774, 2023). "The Western blot results further confirmed that the expressions of HIF1α, VEGFA, and p-STAT3 were all reduced in the tumor tissue of the shSHMT2 group." (PMID 37108312, 2023).
tumor (continued). "Some DEGs have been proved to play an important role in regulating tumor cell invasion ability such as WNT7A, VEGFA, EFEMP1, TRPV2, and FOXC2, whose expressions are consistent with the phenotype (see Results)." (PMID 35755807, 2022). "The results showed that the α-SMA, VEGFA and HGF transcriptional levels in the tumor tissue of the ligustilide-treated group were significantly reduced compared to the control group (PBS)." (PMID 35626012, 2022). "VEGFA is often overexpressed in CRC and is considered to be a key factor in inducing tumor angiogenesis, which plays an important role in tumorigenesis, tumor development, and metastasis." (PMID 35992800, 2022). "The overexpression of some certain ARGs, such as vascular endothelial growth factor A (VEGFA), neuropilin-1 (NRP1) and PlexinA2 (PLXNA2), were found in PCa and their overexpression correlated with tumor metastasis and poorer prognosis." (PMID 35836112, 2022). "A study showed that RAB11B-AS1, a long noncoding RNA, enhances the expression of VEGFA and ANGPTL4 in hypoxic BC cells in a HIF2α-dependent manner, leading to tumor angiogenesis and metastasis." (PMID 36532768, 2022). "It has been shown that miRNA-128 inhibits the expression of CD276, and high levels of CD276 promote tumor growth; furthermore, CD276 promotes tumor angiogenesis and increases the expression of VEGFA by activating the NF-κB pathway." (PMID 36358792, 2022). "In recent years, studies have identified VEGFA and CXC chemokines as important participants in angiogenesis, particularly tumor angiogenesis." (PMID 36246978, 2022). "Then western blotting results from isolated tumor tissues showed that the protein levels of p-SIK1, SIK1 and E-Ca were upregulated, while VEGFA expression was downregulated in LKB1 overexpression group." (PMID 35912012, 2022). "Further mechanistic detection revealed that miR-210 negatively regulated EFNA3 expression and participated in the PI3K/AKT/VEGFA or Wnt/Β-catenin/RHOA pathways, thus promoting tumor angiogenesis and cellular permeability." (PMID 36466111, 2022). "Vascular endothelial growth factor-A (VEGF-A), also called VEGF, is considered to be a major regulatory factor of tumor angiogenesis, which can stimulate tumor angiogenesis and increase tumor vascular permeability." (PMID 35846998, 2022). "It is well established that the pro-angiogenic factor VEGFA and its receptor VEGFR2 are principally responsible for tumor angiogenesis." (PMID 36494333, 2022). "Tumor tissues formed from MIIP-overexpressing MDA-MB-231 cells had decreased levels of CD34 and VEGFA, compared with that from control cells." (PMID 36130933, 2022). "The IHC data revealed that the expression of VEGFA, CA9, and DERL3 in CC specimens was more obvious as opposed to that in normal samples, while the expression of RNF130 was decreased in tumor tissues." (PMID 35935576, 2022). "Regarding the growth factor category, we also found that cluster 6 OS cells likely produce VEGFA, which binds to ITGB1 receptors on endothelial cells (ECs) to regulate their migration and promote new vessel formation and tumor metastasis." (PMID 35463309, 2022). "Inhibiting the production of vascular endothelial growth factor A (VEGFA) can inhibit angiogenesis, thereby inhibiting tumor growth." (PMID 35626012, 2022). "In line with this reasoning, we further confirmed that BMP receptor inhibitors successfully suppressed tumor growth, as well as ID1, HIF-1α, VEGFA, and VEGFR2 expression in HCC xenograft tumors." (PMID 35163396, 2022). "Using tumor metastasis PCR array and luciferase reporter assay, we find that miR-29c directly targets the 3'-UTR of VEGFA and plays critical roles in the process of metastasis inhibition through VEGFA/VEGFR2/ERK pathway." (PMID 36484007, 2022). "The transmission of anti-VEGFA/CCL2/pre-miR-1, anti-miR-31, and pre-miR-206 inhibits tumor growth, tumor angiogenesis, and lung metastasis when administered systemically." (PMID 35909469, 2022).
tumor (continued). "Then RNA was extracted from tumor tissue, and qRT-PCR showed that the expression of NEAT1, IL-34, VEGFA, SPINK1, S100A14, and P4HA2 was downregulated and the expression of CCNE2 was upregulated in NEAT1 knockdown tumor tissue." (PMID 36213831, 2022). "On the other hand, Gepia database revealed that in CC tumor tissues, RSF-1 expression is positively correlated with VEGFA, AKT1 and GSK3β expression." (PMID 36056431, 2022). "Recent studies have confirmed that TAMs can secret pro-angiogenic factors such as VEGFA and MMP9 and thereby promote tumor angiogenesis." (PMID 35436935, 2022). "Vascular endothelial growth factor A (VEGF-A), a pro-angiogenetic chemokine and protease secreted by TAMs promotes tumor angiogenesis." (PMID 36341388, 2022). "Well-known tumor-related genes were found in this ranking, such as ERBB3 (24th rank), VEGFA (75th rank), and ERBB2 (365th rank)." (PMID 35626066, 2022). "At the same time, the platform released sunitinib and active oxygen to induce apoptosis and inhibit tumor angiogenesis, with increased expression of cleaved PARP and decreased levels of VEGFA, HIF-1α, survivin, and p-STAT3." (PMID 35784750, 2022). "This should be interpreted as suppressed VEGFA/VEGFR2 signaling in NPC cells, since the tumor parenchyma constitutes the majority of NPC tissues, and the results are also in accordance with our discovery in HUVECs." (PMID 34975330, 2022). "In the tumour cells, cabozantinib interrupts VEGFR1/VEGFR2/c-KIT/TIE2 pathways, downregulating angiogenic factors (HIF1α, VEGFA) and vascular remodelling factors (MMP2, MMP9)." (PMID 35106125, 2022). "The increased production of vascular endothelial growth factor A (VEGF-A), triggered by the hypoxic stimulus during neo-angiogenesis, shifts the tumor microenvironment (TME) towards immune suppression." (PMID 36294987, 2022). "In experimental studies, metformin induced programmed cell death of cancer cells with inhibition of cell signals, such as vascular endothelial growth factor A (VEGFA), with reduced vascularization of tumor cells." (PMID 35455439, 2022). "In colon cancer, CAF-derived IL-6 induces VEGFA production in an autocrine or paracrine manner, and CAF-derived IL-8 is induced by the autocrine Chitinase 3-like 1, which both promote tumor angiogenesis." (PMID 35327514, 2022). "The induction of tumor hypoxia by 4T-Trap upregulated VEGFA expression, which motivated the authors’ targeting of both the TGF-β and VEGFA pathways in PyMT and MC38 tumor models." (PMID 35577211, 2022). "We found that TMAO enhanced the secretion of vascular endothelial growth factor A (VEGFA) by CRC HCT-116 cells and promoted tumor proliferation." (PMID 35832644, 2022). "Our study demonstrated that macrophages facilitate proliferation, migration, invasion, and tube formation in TECs by secreting VEGFA and MMP9, confirming the promoting effect of TAMs on tumor angiogenesis." (PMID 35436935, 2022). "VEGFA is an angiogenic progenitor, and HIF-1α is an upstream factor of VEGFA and a key effector in the tumor microenvironment, both of which regulate angiogenesis." (PMID 35903690, 2022). "We discovered that only MES1-like tumor cells, MES2-like tumor cells, and TAM-1 expressed the VEGFA in GBM." (PMID 35669791, 2022). "This analysis showed overexpression of the oncogenes VEGFA and NFE2L2, while KRAS was slightly reduced, in tumor samples of HNC." (PMID 35806488, 2022). "With marked patient occupancy (GBC6), Macro04 exhibited versatile tumor-promoting roles, including cytokine production (e.g., TNFAIP3, CXCL3), pro-angiogenesis (e.g., VEGFA), and ECM remodeling (e.g., SPP1) 28,36,37." (PMID 36198671, 2022). "In TME, a hypoxic environment leads to tumor resistance to PD-1/PD-L1, while apatinib can inhibit HIF/VEGFA to increase the sensitivity of immune checkpoint blockade agents and activate NK、CD4+ or CD8+ T cells." (PMID 35844616, 2022).
tumor (continued). "Consistently, IHC analysis revealed that swimming significantly downregulated CD31, HIF-1α, VEGFA, and VEGFR2 protein expression in tumor tissues." (PMID 35291563, 2022). "HIF1α stimulates vascular endothelial growth factor A (VEGFA) gene transcription, which promotes angiogenesis, thereby increasing nutrient availability and oxygen supply to hypoxic tumor areas." (PMID 35193955, 2022). "Molecular mechanism investigation revealed that circPOSTN exerted its tumor-promoting effects by acting as a ceRNA to sponge miR-219a-2-3p and therefore upregulating STC1 and VEGFA expressions." (PMID 35927233, 2022). "VEGFA belongs to the VEGF family (vascular endothelial growth factor; VEGFA, VEGFB, VEGFC, VEGFD, placenta growth factor [PGF]) and represents the best characteristics for angiogenesis to promote tumor growth and systemic metastasis." (PMID 35203290, 2022). "Another example about the link between VEGF and CCL2 is that the concurrent use of anti-VEGFA (bevacizumab) and anti-CCL2 therapy inhibits tumor angiogenesis and growth more effectively than treatments alone in CRCs with ETV5 high expression." (PMID 35935996, 2022). "Genes involved in ‘VEGFA-VEGFR2 signaling’, ‘response to wounding’, ‘response to hypoxia’, and ‘angiogenesis’, which related to tumor progression, were highly expressed in the EP1 cluster compared to the other clusters." (PMID 36551576, 2022). "Tumor fibrosis was negatively correlated with patient prognosis (r = −0.6499, p = 0.002) as was PLGF and VEGFA expression." (PMID 36272973, 2022). "VEGFA is a crucial gene for the formation of blood vessels and angiogenesis (VEGFA NIH), during which the new blood vessels supply nutrients to a tumour and increase tumorigenesis." (PMID 36923728, 2022). "VEGFA increases vascular permeability and binds VEGF-R2 in the tumor microenvironment, consequently favoring tumor angiogenesis." (PMID 35785190, 2022). "However, anti-angiogenic drugs may promote tumor progression and distant metastasis, which may be related to tumor hypoxia and the expression of vascular endothelial growth factor A, fibroblast growth factor, ephrin A1, and the activation of the proto-oncogene c-Met." (PMID 36248960, 2022). "LncRNA F630028O10Rik is a novel lncRNA that can interact with miR‐223‐3p and results in VEGFA and VEGFR2 suppression, thereby regulating tumor angiogenesis and inhibiting tumor growth and progression." (PMID 35918758, 2022). "Upregulated genes included VEGFA, NDUFA4L2, NNMT2, and PLIN2, all previously shown to be involved in tumor development and progression 36,37." (PMID 36180422, 2022). "In the current study, we analyzed the expression of HBA, VEGFA, and CSPG4 genes, and meanwhile evaluated the vascular and pericyte density with immunohistochemical analysis of 50 colorectal patients’ tumor tissue." (PMID 36422502, 2022). "highlights six genes (VEGFA, KDR, ESM1, CD34, PECAM1, and ANGPTL4), but only four of them were expressed by endothelial cells while VEGFA and ANGPTL4 were mainly expressed by tumor cells." (PMID 36423636, 2022). "In vivo, after long-term choline feeding in tumor-bearing mice, circulating TMAO levels, tumor volume, new blood vessel formation, and VEGFA and CD31 amounts were increased significantly." (PMID 35832644, 2022). "RAS/PI3K promotes the expression of angiogenic factors, e.g., vascular endothelial growth factor A (VEGFA), via cyclooxygenase 2 (COX2) and activation of tumor angiogenesis and coagulation pathways leads to adaption to sotorasib." (PMID 36483040, 2022). "VEGFA binds with VEGFR 1 and 2 inducing both physiological and pathological angiogenesis, including tumour angiogenesis." (PMID 35681586, 2022). "CAFs, in turn, recruit endothelial and immune cells to the tumour via secreting a variety of chemokines and growth factors including VEGFA (vascular endothelial growth factor A), PDGF (platelet-derived growth factor) and HGF (hepatocyte growth factor)." (PMID 34982945, 2022).
tumor (continued). "With these in the background, we aimed to investigate the effect of the presence of vessel and pericyte density, and VEGFA and CSPG4 expressions in the tumor tissue, on the efficacy of the bevacizumab in metastatic or recurrent colorectal cancer patients." (PMID 36422502, 2022). "This TAM subtype also owns a high level of VEGFA, CXCL8, and IL1β, similar to previously reported TAM induced from monocyte with factor-1a stabilization in solid ovarian cancer that promoted tumor inflammation and metastasis." (PMID 35935940, 2022). "Treatment with VEGFA and VEGFC inhibitors decreased tumor metastasis into LNs and lungs in a mouse mammary-gland cancer model." (PMID 35626729, 2022). "Given the pivotal roles of VEGFA and PDGF-BB in tumor angiogenesis, we conducted ELISA assay on these two genes and found that only VEGFA is significantly down- and up-regulated by PELP1 depletion and overexpression, respectively." (PMID 35053547, 2022). "The proangiogenic factors vascular endothelial factor A (VEGFA) and CD31 were used as endothelial markers to measure angiogenesis in the tumours." (PMID 35342361, 2022). "Vascular endothelial growth factor-A (VEGFA; also known as VEGF) is one of the main factors driving the generation and expansion of tumor vascular beds." (PMID 36483049, 2022). "In conclusion, swimming significantly attenuates the growth of CT-26 cell-derived tumors in vivo, reduces tumor angiogenesis, and downregulates the expression of HIF-1α, VEGFA, and its receptor VEGFR2." (PMID 35291563, 2022). "Despite a greater proportion of M1 macrophages in the TME, M2 macrophages expressed higher gene level of CD163, MRC1 (CD206), TGF-β, IL10, VEGFA, and MMP9, which exhibited stronger tumor-promoting ability." (PMID 35033156, 2022). "Specifically, in the tumour region, we observed enrichment of PPIB and UGT2B15 and IFI27, NDRG1, BHLHE40 and VEGFA." (PMID 35109839, 2022). "Lungs were analyzed by IHC for two markers related to anti-tumor immunity: CD8+ T cell infiltration and VEGFA." (PMID 35008514, 2021). "LINC000173.v1 upregulates the expression of VEGFA through miR-511-5p sponging and inhibition of LINC000173.v1 using ASOs resulted in decreased tumor growth and enhanced cisplatin sensitivity." (PMID 33740988, 2021). "MTR OralGem restricted tumor angiogenesis by regulating thrombospondin-1 (TSP-1) and vascular endothelial growth factor A (VEGFA) expression." (PMID 33920884, 2021). "Although only VEGFA is shared between the mouse and human reads, R-ketorolac alters genes within the HIF-1 pathway in both the human and mouse components of the tumor." (PMID 33413202, 2021). "Gliclazide is an anti-diabetic drug inhibiting VEGFA, a known interactor of KDR, and is significantly upregulated in MPM tumour (Log2FC = 1.83, p-value = 0.0018)." (PMID 33916178, 2021). "TME in the context of obesity increases tumor-infiltrating myeloid cells with activated NLRC4 inflammasomes, thereby activating IL-1β and driving disease progression through adipocyte-mediated VEGFA expression and angiogenesis." (PMID 34063828, 2021). "Angiogenesis and tumor progression were influenced by exosome mediated Wnt4/β-catenin signaling in CRC and by vascular endothelial growth factor A (VEGF-A) enriched exosomes in brain endothelial cells." (PMID 33477340, 2021). "For the first time, our work confirms that S1PR1 affects tumor growth and angiogenesis via the S1PR1/P-STAT3/VEGFA axis." (PMID 34059068, 2021). "TAMs modulate the CCA microenvironment by secreting TNFα, TGFβ (tumor growth factor-β), IL6, IL10, and VEGF-A (vascular endothelial growth factor-A), which support epithelial-to-mesenchymal transition (EMT), tumor growth, and metastasis." (PMID 33579265, 2021). "Knockdown of VEGFA in MDA‐MB‐231 cells resulted in significant phenotype changes (the cellular networks of VM vs. decreased branching and tumor spheroid morphology) similar to that in TM‐treated cells." (PMID 34320274, 2021).